TMEM41B (transmembrane protein 41B)
Description:
Phospholipid scramblase involved in lipid homeostasis and membrane dynamics processes. Has phospholipid scramblase activity toward cholesterol and phosphatidylserine, as well as phosphatidylethanolamine and phosphatidylcholine. Required for autophagosome formation: participates in early stages of autophagosome biogenesis at the endoplasmic reticulum (ER) membrane by reequilibrating the leaflets of the ER as lipids are extracted by ATG2 (ATG2A or ATG2B) to mediate autophagosome assembly. In addition to autophagy, involved in other processes in which phospholipid scramblase activity is required. Required for normal motor neuron development (By similarity). (Microbial infection) Critical host factor required for infection by human coronaviruses SARS-CoV-2, HCoV-OC43, HCoV-NL63, and HCoV-229E, as well as all flaviviruses tested such as Zika virus and Yellow fever virus. Required post-entry of the virus to facilitate the ER membrane remodeling necessary to form replication organelles.
Synonyms: KIAA0033
Tractability: Antibody: UniProt predicts a signal peptide or a membrane-spanning region. PROTAC: ubiquitination databases record sites on it; its protein half-life has been measured.
Gene: Protein-coding gene on chromosome 11 (9,280,654 to 9,314,636, reverse strand). Ensembl gene ENSG00000166471.
Subcellular location: Endoplasmic reticulum membrane; Endomembrane system; Cytoplasm
Subcellular location (Human Protein Atlas): Peroxisomes
Gene Ontology:
Molecular function: phospholipid scramblase activity; protein binding
Biological process: autophagosome assembly; host-mediated perturbation of viral RNA genome replication; intracellular lipid transport; plasma membrane phospholipid scrambling
Cellular component: cytoplasm; endomembrane system; endoplasmic reticulum membrane; mitochondria-associated endoplasmic reticulum membrane contact site
Genetic constraint (gnomAD): Loss-of-function variants: 6 observed, 14.19 expected, observed/expected ratio (o/e) 0.42, 90% interval 0.23 to 0.83. The upper end of that interval is the gene's LOEUF score, 0.83, which puts it in group 3 of 6, group 1 being the genes least tolerant of losing a copy. Missense variants: 215 observed, 227.05 expected, observed/expected ratio (o/e) 0.95, 90% interval 0.85 to 1.06. Synonymous variants: 107 observed, 83.79 expected, observed/expected ratio (o/e) 1.28, 90% interval 1.09 to 1.5.
Homologues: Orthologues: chimpanzee TMEM41B (99% identical), macaque TMEM41B (97% identical), rabbit TMEM41B (95% identical), dog TMEM41B (94% identical), rat Tmem41b (93% identical), pig TMEM41B (92% identical), mouse Tmem41b (90% identical), tropical clawed frog tmem41b (80% identical), guinea pig TMEM41B (77% identical), zebrafish tmem41b (71% identical), Drosophila melanogaster stas (47% identical), Caenorhabditis elegans egli-1 (43% identical). Paralogues in human: TMEM41A (26% identical), TMEM64 (14% identical).